ENSG00000201036
Synonyms: LOC124903417
Gene: Small nucleolar RNA gene on chromosome 14 (100,979,002 to 100,979,090, forward strand). Ensembl gene ENSG00000201036.
Gene Ontology:
Biological process: RNA processing
Cellular component: nucleolus
Homologues: Paralogues in human: SNORD114-17 (61% identical), SNORD114-3 (61% identical), SNORD114-15 (60% identical), SNORD114-12 (58% identical), SNORD114-14 (58% identical), SNORD114-13 (57% identical), SNORD114-18 (57% identical), SNORD114-21 (57% identical), SNORD114-9 (57% identical), SNORD114-10 (56% identical), SNORD114-22 (56% identical), SNORD114-23 (56% identical), and 27 more.